TERF2 (telomeric repeat binding factor 2)
Description:
Binds the telomeric double-stranded 5'-TTAGGG-3' repeat and plays a central role in telomere maintenance and protection against end-to-end fusion of chromosomes. In addition to its telomeric DNA-binding role, required to recruit a number of factors and enzymes required for telomere protection, including the shelterin complex, TERF2IP/RAP1 and DCLRE1B/Apollo. Component of the shelterin complex (telosome) that is involved in the regulation of telomere length and protection. Shelterin associates with arrays of double-stranded 5'-TTAGGG-3' repeats added by telomerase and protects chromosome ends; without its protective activity, telomeres are no longer hidden from the DNA damage surveillance and chromosome ends are inappropriately processed by DNA repair pathways. Together with DCLRE1B/Apollo, plays a key role in telomeric loop (T loop) formation by generating 3' single-stranded overhang at the leading end telomeres: T loops have been proposed to protect chromosome ends from degradation and repair. Required both to recruit DCLRE1B/Apollo to telomeres and activate the exonuclease activity of DCLRE1B/Apollo. Preferentially binds to positive supercoiled DNA. Together with DCLRE1B/Apollo, required to control the amount of DNA topoisomerase (TOP1, TOP2A and TOP2B) needed for telomere replication during fork passage and prevent aberrant telomere topology. Recruits TERF2IP/RAP1 to telomeres, thereby participating in to repressing homology-directed repair (HDR), which can affect telomere length (By similarity).
Synonyms: TRBF2; TRF2
Tractability: Small molecule: it has a high-quality binding pocket. PROTAC: UniProt records ubiquitination sites on it; ubiquitination databases record sites on it; its protein half-life has been measured; a small molecule that binds it is known.
Gene: Protein-coding gene on chromosome 16 (69,355,464 to 69,408,571, reverse strand). Ensembl gene ENSG00000132604.
Subcellular location: Nucleus; Chromosome, telomere
Subcellular location (Human Protein Atlas): Nuclear bodies; Nucleoplasm
Pathways (Reactome):
Cell Cycle: Inhibition of DNA recombination at telomere; Packaging Of Telomere Ends; Polymerase switching on the C-strand of the telomere; Processive synthesis on the C-strand of the telomere; Removal of the Flap Intermediate from the C-strand; Telomere C-strand (Lagging Strand) Synthesis; Telomere C-strand synthesis initiation; Telomere Extension By Telomerase
DNA Repair: Cleavage of the damaged purine; Cleavage of the damaged pyrimidine; Recognition and association of DNA glycosylase with site containing an affected purine; Recognition and association of DNA glycosylase with site containing an affected pyrimidine
Cellular responses to stimuli: DNA Damage/Telomere Stress Induced Senescence
Reproduction: Meiotic synapsis
Gene Ontology:
Molecular function: double-stranded telomeric DNA binding; enzyme binding; G-rich strand telomeric DNA binding; protein binding; protein homodimerization activity; protein-containing complex binding; telomerase activity; telomeric DNA binding
Biological process: negative regulation of cellular senescence; negative regulation of t-circle formation; negative regulation of telomere capping; negative regulation of telomere maintenance; negative regulation of telomere maintenance via recombination; negative regulation of telomere maintenance via telomerase; negative regulation of telomere maintenance via telomere lengthening; negative regulation of telomeric D-loop disassembly; positive regulation of protein localization; positive regulation of telomere maintenance; protection from non-homologous end joining at telomere; protein localization to chromosome, telomeric region; regulation of telomere maintenance; regulation of telomere maintenance via telomerase; telomere capping; telomere maintenance; telomeric D-loop disassembly; telomeric loop formation; cellular senescence; negative regulation of telomere maintenance via semi-conservative replication; negative regulation of telomere single strand break repair; axonal transport of messenger ribonucleoprotein complex; RNA-templated DNA biosynthetic process
Cellular component: chromosome, telomeric region; nuclear body; nuclear telomere cap complex; nucleoplasm; nucleus; shelterin complex; axon; male germ cell nucleus; telomere cap complex
Genetic constraint (gnomAD): Loss-of-function variants: 15 observed, 52.03 expected, observed/expected ratio (o/e) 0.29, 90% interval 0.19 to 0.44. The upper end of that interval is the gene's LOEUF score, 0.44, which puts it in group 1 of 6, group 1 being the genes least tolerant of losing a copy. Missense variants: 523 observed, 638.91 expected, observed/expected ratio (o/e) 0.82, 90% interval 0.76 to 0.88. Synonymous variants: 289 observed, 261.04 expected, observed/expected ratio (o/e) 1.11, 90% interval 1 to 1.22.
Homologues: Orthologues: chimpanzee TERF2 (99% identical), macaque TERF2 (99% identical), dog TERF2 (92% identical), pig TERF2 (92% identical), rabbit TERF2 (91% identical), guinea pig TERF2 (87% identical), mouse Terf2 (85% identical), rat Terf2 (85% identical), tropical clawed frog terf2 (32% identical), zebrafish terfa (23% identical). Paralogues in human: TERF1 (19% identical).